CD24 (CD24 molecule)
Diseases named in the same sentence as CD24 in open-access papers (continued):
Sharing a sentence is not in itself a finding about the gene and the disease.
tumor (continued). "In our cohort, flow cytometry analysis revealed a higher number of leukocytes expressing a significantly higher percentage of CD24+/CD11b− PBLs among HN cancer patients peripheral blood samples and in immunohistochemistry of tumor tissue compared with normal controls." (PMID 38138858, 2023). "macroC0 and macroC3 had high expression of CD24, a protein important for tumour radioresistance." (PMID 37784253, 2023). "Therefore, inhibiting these CD24-related upstream molecules of regulatory signaling pathways can effectively prevent tumor invasion and immune escape, regulate tumor microenvironment, and thereby exert a positive effect on regressing tumor progression." (PMID 37919766, 2023). "CD24 also plays a part in the E-selectin-mediated movement of tumor cells across the surface of vascular endothelium, and it activates integrin subunits, enabling tumor cells to bind to extracellular matrix components and increase their mobility." (PMID 38313430, 2023). "Therefore, we selected CD44 and CD24 as tumor cell stemness markers in GC and detected their expression." (PMID 37005676, 2023). "In addition, they obtained the enhancement of anti-tumor immunity by macrophages when monoclonal antibodies were used to block of CD24/Siglec-10 anti-phagocytic signal which strongly supports the Siglec-10 inhibition activity against phagocytosis." (PMID 36109471, 2023). "Increasing trials is focusing on the strategy not only on blocking the CD24 on the surface of tumor cells, but also on targeting the CD24 and Siglec-10 genes, as well as targeting on the binding of CD24-Siglec-10 signal pathway (new insight and strategy in tumor immunity therapy field)." (PMID 37359556, 2023). "SWA11 monoclonal antibody could bind CD24-expressing cells specifically and then inhibit the proliferation of tumor cells." (PMID 37359556, 2023). "Expression of EpCAM, Vimentin and CD24 was then analysed for every nucleated cell in every imaging field that included both tumour and stroma (3500 manually curated imaging fields across the 24 tumours)." (PMID 37975646, 2023). "Secondly, CD24 plays a crucial role in promoting tumor cell metastasis via multiple mechanisms." (PMID 38313430, 2023). "cG7-sTGFBR2 is able to transport TGFBR2 into the tumor microenvironment by targeting CD24." (PMID 37484024, 2023). "Notably, administering anti-CD24 antibodies significantly reduced tumor growth within murine models." (PMID 37822610, 2023). "Interestingly, tumor-derived exosomes isolated from patient plasma also showed a threefold increase in CD24 as identified by the Exosearch chip method." (PMID 36831617, 2023). "By contrast, CD24-blocking antibodies did not have a significant therapeutic effect on CD24-deficient tumor cells." (PMID 37484024, 2023). "In the non-tumour cells, only 0.8% (29/3687) were EpCAM+Vim+CD24+." (PMID 37975646, 2023). "Experimental studies during the last decade have provided evidences for the roles of CD24 overexpression in tumor anchorage-independent proliferation, migration, invasion, and apoptosis inhibition of cancer cells, as well as adhesive function during hematogenous dissemination of cancer cells." (PMID 37919766, 2023). "CD24 is known to promote tumor growth and metastasis in various malignancies, including OSCCs." (PMID 37664387, 2023). "We postulated that CD24 blockage with a monoclonal antibody targeting CD24 could have anti-tumor therapeutic benefits while preserving a good safety profile and synergistic therapeutic effects when used in conjunction with other anti-tumor antibodies." (PMID 37846296, 2023). "In various cancers, CD24 expressed by cancer cells is described as “do not eat me” signal, which is identified associated with tumor growth in vitro and in vivo." (PMID 36882451, 2023).
tumor (continued). "Our tumor vaccine induced the most abundant immune cell infiltrate in cardiac tissue, which provides CD24-Fc with the most Siglec binding sites and thus a positive feedback loop for CD24-Fc to inhibit the autoimmune response." (PMID 37346042, 2023). "The novel Nanosphere‐AntiCD24, synthesized by linking nanospheres with CD24 antibody, accurately regulates the degradation of CD24 protein and partially restores the phagocytic function of macrophages toward tumor cells by blocking the CD24/Siglec‐10 signaling pathway." (PMID 36866919, 2023). "Studies suggested that the CD24-targeted antibody could offer robust cancer cell-killing effects and block the vicious cycle for tumor recurrence from CSCs." (PMID 37919766, 2023). "In summary, while CD24-targeted immunotherapy holds promise in the treatment of cancer and non-neoplastic diseases, numerous questions related to its clinical application, efficacy, safety, and combination strategies still need to be addressed through rigorous research and clinical trials." (PMID 38313430, 2023). "Our results showed that CD24 was a tumor-specific “don’t eat me” signal in OS." (PMID 36596773, 2023). "In humans, to negatively regulate the immune response to proteins released by damaged cells, purified CD24 derived from tumor cell lines partners with Siglec-5, whereas CD24 isolated from human placenta clearly binds to Siglec-10, and only CD24-Signlec-10 is related to phagocytosis function." (PMID 37919766, 2023). "Gene ablation of CD24 or Siglec-10 and monoclonal antibodies to block the CD24-Siglec-10 interaction enhanced the phagocytosis of CD24-expressing tumors, resulting in a decrease in macrophage-dependent tumor growth." (PMID 35585567, 2022). "In addition to the role of Akt, Erk1/2 and mTOR pathways in tumor transition as well as CD24 and its influence on immune competence in the TME were analyzed." (PMID 36552039, 2022). "Interestingly, CD24(+)CD44(+)EpCAM(+) CICs from the differentiated ductal-like cancer cells were found in the tumor mass." (PMID 35673567, 2022). "Upon ectopic CD24 expression, the gene CD44 (encoding cell surface adhesion receptor CD44) was downregulated, which has been shown to be expressed in cancer cells and regulates tumor cell invasion and metastasis." (PMID 36016357, 2022). "The mesenchymal cluster included a stem-cell like profile with upregulation of CD44 and downregulation of CD24, which is consistent with the simultaneous presence of EMT and stem-like features of tumour cells associated with metastatic potential of cancer cells." (PMID 35493092, 2022). "Furthermore, in tumor tissues, the expression of CD24, another known innate immune checkpoint, is notably strong compared to the expression of CD47." (PMID 35978372, 2022). "Furthermore, pyrotinib treatment or CD24 silencing both resulted in the decreased expression of siglec-10 in macrophages co-incubated with the cultured tumor cell supernatant." (PMID 36231025, 2022). "Finally, the surface receptor CD24 was exclusively expressed on tumor cells and interacts with SIGLEC10 on macrophages in the immune cells." (PMID 35688160, 2022). "Furthermore, CD24 mAb treatment or CD24 deletion in tumor cell lines or mice can improve tumor cell phagocytosis, control tumor development, and lengthen life in vitro or in vivo by recovering the macrophages’ capacity." (PMID 36497444, 2022). "A recent study has shown that CD24−/CD44+ CSCs were associated with cell proliferation and tumor progression, whereas ALDH+ CSCs were more associated with metastasis, indicating that these two markers enrich for different CSC populations with diverse phenotypes." (PMID 35053617, 2022). "Furthermore, in many tumor types, CD24 is an anti-phagocytic signal expressed on the surface of tumor cells." (PMID 35965509, 2022). "In addition to making tumors more aggressive, it has been verified that CD24 renders tumors resistant to chemotherapy, resulting in tumor recurrence and deterioration after chemotherapy." (PMID 35659268, 2022).
tumor (continued). "While being present in varying levels in different healthy cells and tissues, CD24 is also found to be upregulated in some cancer cells, with studies suggesting it to be an important marker for prognosis and diagnosis for certain types of tumor cells." (PMID 36016357, 2022). "CD24 is a glycosylated phosphatidylinositol cell surface protein that mediates cancer cells, activated platelets, vascular endothelial cells, lymphatic circulation, and blood migration, resulting in tumor invasion and distal metastasis." (PMID 35938128, 2022). "In addition, Siglec-10 inhibits TCR-associated kinase by binding to CD24 or CD52 to suppress T-cell activation and promote tumor immune escape." (PMID 35418152, 2022). "Moreover, tumor-associated macrophages (TAM) appear to express Siglec-10 genes profoundly, proposing the CD24-Siglec10 inhibitory signaling cascade as a potential strategy for cancers to evade inflammatory responses efficiently." (PMID 37551166, 2022). "In addition to the regulatory mechanism of CD24 expression, the biological features of tumor cells in CD24‐expressing DLBCL should be investigated in further studies." (PMID 35289116, 2022). "FACS analysis showed that CD24+MDSC-DCs from tumor patients could significantly inhibit CD4+T cells from differentiating into Tregs (Fig. 7DandE)." (PMID 35707772, 2022). "Overexpression of HIF1A promotes production of CD24, which leads to tumor growth and metastasis." (PMID 35659268, 2022). "For CD24 mAb treatment, pro-phagocytic activity was strongest in M2c macrophages, which are typically reported to promote anti-inflammatory and pro-tumoral responses in the tumor microenvironment (TME)." (PMID 35625912, 2022). "Interestingly, the transcriptional expression of CD24 was significantly downregulated in primary OSCC tumor samples compared to that of normal oral mucosal tissues." (PMID 36498950, 2022). "Similarly, CD90+CD24+ CSCs isolated from pulmonary metastases are the only tumor cell population that efficiently initiates secondary metastases." (PMID 35563509, 2022). "The CD24-SIGLEC10 axis inhibits phagocytosis of tumor cells by macrophages." (PMID 36468012, 2022). "Moreover, stem cell markers such as CD44/CD24 and high levels of ALDHA1 can predict stemness in triple-negative tumor features; also, more than four lymph nodes are associated with unfavorable outcomes." (PMID 36120232, 2022). "Additionally, TCF64-ORF-T expressed higher levels of the stemness markers, CD44 and ALDH1, but lower level of CD24 as compared to the control tumor TCF64-Ctl-T." (PMID 36359766, 2022). "Next, we tried to figure out if depletion of CCL5 protein could induce tumor patients-derived MDSCs into CD24+MDSC-DCs with similar antitumor function as murine CD24+MDSC-DCs." (PMID 35707772, 2022). "CD24 is an important factor in the crosstalk of tumor cells with the somatic microenvironment." (PMID 34293822, 2022). "Supporting this notion, CD24 induced tumor growth, invasion, and metastasis in different cancers." (PMID 35884847, 2022). "Indeed, the enrichment of TNBC tumours with CD44+/CD24− cells confers them to a higher proliferation, migration, invasion, and tumorigenic capacity." (PMID 36077812, 2022). "In addition, CD24 expression was associated with serum prostatic specific antigen (PSA) relapse (2/5) and tumor progression (1/5)." (PMID 33806857, 2021). "Previous studies reported CD24 as an inhibitor for neurite outgrowth in mice and that expression was related to the differentiation state in human NB suggesting an activation of CD24 in less differentiated tumor samples." (PMID 34026614, 2021). "Targeting the CD24-Siglec-10 signaling axis stands as a promising approach for cancer immunotherapy whereby blocking Siglec-10 on human MDMs resulted in a significant increase in the phagocytic capacity of tumor cells." (PMID 34281268, 2021).
tumor (continued). "Moreover, patients in the C1 group, with a low frequency of CSCs and higher frequency of CD44-/CD24- tumor cells, also had a worse DFS than those with a lower frequency of CD44-/CD24- tumor cells in the C0 group." (PMID 34318746, 2021). "Since the role of CD44 and CD24 in tumor metastasis and invasiveness has previously been reported, CSNK1G2 may, in part, contribute to tumor progress." (PMID 33861751, 2021). "In addition, the ADAM-10 expression level was increased in RT-R-MDA-MB-231 tumor tissue compared to MDA-MB-231 tumor tissue and was even higher in CD24−/low/CD44+ tumor tissue." (PMID 34502547, 2021). "However, the expression of the NK cell inhibitory ligand HLA-E exhibited the opposite pattern, with lower expression in MDA-MB-231 tumor tissue than in RT-R-MDA-MB-231 or CD24−/low/CD44+ tumor tissue." (PMID 34502547, 2021). "Furthermore, we found that residual tumor cells in MTB;TetO-Wnt1;TTC;rYFP mice were enriched ~ 8-fold for CD24+Thy1+ tumor cells compared to primary tumors." (PMID 34088357, 2021). "CD24 expression was also associated with PSA relapse (2/5) and tumor progression (1/5)." (PMID 33806857, 2021). "A large number of subpopulations with enhanced tumor initiating capacity have been identified, especially several markers, including CD24, CD44, CD117, CD133, ABCG, ESA and ALDH, which are widely used in the literature to identify and investigate human epithelial cancer stem cells." (PMID 33923707, 2021). "Finally, we confirmed the effect of MDA-MB-231, RT-R-MDA-MB-231, and CD24−/low/CD44+ cells on tumor progression in an in vivo xenograft model in mice." (PMID 34502547, 2021). "However, N-cadherin, β-catenin, Snail, and ESM-1 expression levels were increased in RT-R-MDA-MB-231 tumor tissue compared to MDA-MB-231 tumor tissue and were even higher in CD24−/low/CD44+ tumor tissue." (PMID 34502547, 2021). "Some of these signals, such as CD24, may also help tumor cells escape efferocytosis, leading to peripheral tissue damage." (PMID 34926460, 2021). "Similarly, ovarian-cancer-derived sEVs express CD24 and EpCAM, which are tumor-exclusive markers and therefore can differentiate between cancerous and non-cancerous lesions." (PMID 34571921, 2021). "More recently, CD24 was shown to have an intriguing role in tumor evasion from phagocytosis, hypothesized to act as a ‘don’t eat me signal’." (PMID 33915986, 2021). "The specific markers that we analyzed include tumor stem cell markers (CD24, CD44), markers of immunosuppression (CD47, PD-L1), markers of cell adhesion (CD49d, ICAM-1), markers of lymphocytes co-stimulation (CD80, CD86), and markers of antigen presentation (MHC class I, MHC class II)." (PMID 34411144, 2021). "Multiple mechanisms that regulate the adhesion step of this process have been identified, including interactions between tumor cell CD44 and mesothelial fibronectin, tumor cell β1 integrins and mesothelial extracellular matrix, and tumor cell CD24 and mesothelial P-selectin." (PMID 34396026, 2021). "A similar pattern of DFS was observed in TNBC patients and those with a higher frequency of CD44-/CD24- cells had a high risk to develop progressive metastasis at 4 years post tumor resection regardless of chemotherapy." (PMID 34318746, 2021). "Moreover, the levels of tumor metastasis-related molecules, HIF-1α expression, and LOX secretion were increased in RT-R-MDA-MB-231 tumor tissue compared to MDA-MB-231 tumor tissue and were even higher in CD24−/low/CD44+ tumor tissue." (PMID 34502547, 2021). "Recently, the “do not eat me” CD24 signal was shown to interact with the inhibitory receptor sialic acid-binding Ig-like lectin 10 (Siglec-10) on tumor-associated macrophages (TAMs), orchestrating a novel innate immune checkpoint." (PMID 34926460, 2021). "Many studies point to the role of CD24 in tumor growth and cancer progression." (PMID 34575716, 2021).
tumor (continued). "Similarly, the DFS of patients with a high frequency of CD44-/CD24- tumor cells or CD44+/CD24- CSCs was significantly shorter than those with a low frequency of corresponding cells." (PMID 34318746, 2021). "Furthermore, the inhibitory receptor sialic-acid-binding Ig-like lectin 10 (Siglec-10), which is expressed by TAMs, can promote phagocytic evasion when engaged with CD24 expressed on tumor cells." (PMID 34572013, 2021). "Anti-CD24 antibody therapy in both OC cell lines and murine OC models resulted in superior phagocytic clearance of tumour cells by macrophages, and correlating with reduced tumour growth in vivo." (PMID 34944851, 2021). "The combination of anti‐CD47 and anti‐CD24 antibodies could offer robust cancer cell‐killing effects and block the vicious cycle for tumor recurrence from cancer stem cells." (PMID 34363319, 2021). "Moreover, HIF-1α/LOX induction and ESM-1 expression, which are involved in tumor metastasis and progression, were enhanced in CD24−/low/CD44+ cells compared to TNBC and RT-R-TNBC cells." (PMID 34502547, 2021). "A lack of published research directly comparing the ALDH+ and CD44+/CD24- breast CSC populations in the context of patient tumor samples indicates an opportunity for further study to elucidate the mechanism of prostaglandin signaling in breast CSCs and the tumor microenvironment." (PMID 35127497, 2021). "Through M1 conversion, the anti‐CD24 antibody may fundamentally alter the microenvironment that otherwise supports tumor growth." (PMID 34363319, 2021). "Furthermore, following standard chemotherapy or endocrine therapy, the patients with a higher frequency of CD44-/CD24- tumor cells had a significantly shorter DFS than their corresponding patients with a lower frequency of CD44-/CD24- tumor cells." (PMID 34318746, 2021). "Further studies have found that CD47 can affect the polarization of tumor‐associated macrophages, while CD24 has no relevant reports." (PMID 34363319, 2021). "Intracellular localization of CD24 was reported in tumor specimens of various cancers." (PMID 34360932, 2021). "Here, we found that the AD population includes mainly CD90+ cells with highly proliferative rates in vitro but no tumorigenic potential in vivo, whereas the NAD population contains principally tumor cell spheroids (EpCAM+/CD24+) with low proliferative potential in vitro." (PMID 34060699, 2021). "Furthermore, the specific binding of CD24-targeting fluorescence contrast agents to CD24+ tumor cells has been reported in preclinical metastatic cell lines and PDX models, which support its use as a theranostic biomarker." (PMID 33260974, 2020). "Furthermore, we found that immunosuppression was enhanced in the 3D printed tumor models because of the higher levels of IL-8 and CD24." (PMID 32582546, 2020). "In addition, when platelets are aggregated in the TME, they become highly activated due to their binding to tumor cells via P-selectin-CD24 axis." (PMID 33276524, 2020). "It is necessary to comment on the molecular mechanism of inhibiting the activation of immune cells through the interaction between CD24 on tumor cells and Siglec-10 on immune cells, and a treatment strategy of tumors through targeting CD24 on the surface of tumor cells or Siglec-10 on immune cells." (PMID 32765491, 2020). "Furthermore, inhibition of PLK1 blocked the growth of CD44 high/CD24-/low tumour-initiating cells in TNBC." (PMID 32050983, 2020). "Moreover, EMT activation via the Ras-MAPK signalingpathway in normal breast CD44-/CD24+ cells leads to their transformation intoCD44+/CD24- stem tumor cells; additional activation of TGF-β1 enhances theeffect." (PMID 33173593, 2020). "In addition, CD24+ cells were observed at greater frequency in iSOX11 tumours compared to control tumours." (PMID 32909943, 2020). "A blockade of the CD24-Siglec10 binding decreased tumor growth." (PMID 35582213, 2020).